HMGB1 (high mobility group box 1)
Diseases named in the same sentence as HMGB1 in open-access papers (continued):
Sharing a sentence is not in itself a finding about the gene and the disease.
tumor (continued). "Finally, NK cells can also amplify their recruitment at the tumor site by releasing a chemotactic form of HMGB1 molecule upon interaction with tumor cells." (PMID 30930851, 2019). "Notably, β-lap promoted HMGB1-depedent immunogenicity and activated innate sensing to bridge innate and adaptive immune response, and markedly shrunk the tumor mass, and is thus a promising partner for combination with immunotherapy." (PMID 31324798, 2019). "Next, we sought to determine the role of HMGB1 in tumor invasion and metastasis." (PMID 31410208, 2019). "However, while chronic HMGB1 release is detrimental, an acute and sudden release following OV infection triggers tumor-specific immunity with beneficial effects." (PMID 31355131, 2019). "HMGB1 originating from tumor cells promote DC recruitment into the tumor microenvironment." (PMID 31379812, 2019). "So we speculated that high expression of HMGB1 promoted invasion of tumor cells through signaling pathway related to cell adhesion and migration." (PMID 30962261, 2019). "HMGB1 may also be released from tumor cells dying upon chemo- or radiotherapy therefore stimulating and TLR4 leading to DC maturation." (PMID 31695691, 2019). "In addition, tumor metabolism is characterized by an elevation in the rate of intracellular acetylation of HMGB1 by post-translational modification." (PMID 30279967, 2018). "Moreover, damage-associated molecular patterns (DAMPs), such as uric acid, S100 proteins, adenosine triphosphate (ATP) or High-Mobility-Group-Protein B1 (HMGB1), as well as tumor antigens, are released to activate innate and adaptive immune responses." (PMID 30577587, 2018). "In addition to HMGB1, we have found that the expression of its receptor TIM-3 in pre-treatment tumor samples is associated with worse prognosis in adenovirus treated patients." (PMID 29464075, 2018). "Extracellular HMGB1 is thought to induce cancer cell growth, mobility, invasion, and metastasis via binding to specific membrane receptors, including the receptor for advanced glycation end products (RAGE), and blockage of the RAGE-HMGB1 complex suppresses tumor growth and metastasis." (PMID 29850505, 2018). "Thus, tumors with low HMGB1 serum levels displayed distinctly more aggressive tumor growth behavior over time than tumors with high HMGB1 levels (p<0.001)." (PMID 30123419, 2018). "As expected, DHA-37 induced a significant increase of HMGB1 expression in tumor tissue." (PMID 30323180, 2018). "Our data indicate that HMGB1 is secreted by tumor cells, but additional release through immune cells within the tumor microenvironment may contribute to elevated HMGB1 levels." (PMID 30123419, 2018). "And inhibition of the HMGB1-RAGE pathway leads to tumor growth suppression." (PMID 30123419, 2018). "In addition, tumor cell-derived HMGB1 mediates tumor cell-platelet interaction to promote metastasis." (PMID 30292233, 2018). "Our studies converged on a critical role for HMGB1 in tumor cell proliferation after irradiation." (PMID 29844348, 2018). "Indeed, extracellular HMGB1 secreted from dying tumor cells was detected in the medium following treatment with these anticancer agents." (PMID 30258050, 2018). "Conversely, tumor-derived HMGB1 may favor tumor progression and suppress antitumor immunity by promoting IL-10 production in Tregs through RAGE." (PMID 30643519, 2018). "HMGB1 released by activated platelets, activated leukocytes, and necrotic cells influences leukocyte functions, favoring neoangiogenesis, a tumor-permissive environment in experimental models and—possibly via NET induction—favoring a prothrombotic state in tumor-bearing patients." (PMID 29515586, 2018). "Moreover, HMGB1 passively released from dying tumor cells after chemotherapy and radiotherapy or directly secreted from tumor cells promotes regrowth, proliferation and metastasis." (PMID 30258050, 2018).
tumor (continued). "Similarly, to what was observed in organotypic cultures expressing HPV16 oncogenes, invasive tumor areas exhibited strong nuclear HMGB1 staining in all cells." (PMID 29472602, 2018). "Accordingly, VHL downstream hypoxia signaling and tumor hypoxia might both trigger increased HMGB1 secretion, and result in increased VEGF signaling as well as total VEGF levels that bevacizumab can target." (PMID 30123419, 2018). "In addition, the tumor tissues had a significantly higher HMGB1 mRNA expression level as compared to the healthy tissues in HNSCC patients (P<0.001)." (PMID 30245980, 2018). "Moreover, the plasma HMGB1 level is associated with cancer TMN staging, acting as an extracellular signalling molecule during tumor progression." (PMID 29853785, 2018). "Once secreted, HMGB1 binds dendritic cell Toll-Like Receptor 4 on its surface, leading to an effective anti-tumor immune response that may eliminate tumor cells, preventing the spread of metastasis." (PMID 29783720, 2018). "However, since the amount of intracellular HMGB1 is lower, it is estimated that the proinflammatory potential of the treated tumor cells is diminished in the same way." (PMID 30279967, 2018). "In recent years, the alarmin HMGB1, which can be massively released within the tumor microenvironment, has also been described to form a complex with the chemokine CXCL12 enhancing CXCR4-mediated signaling, thus providing an additional regulation of the activity of the chemokine system." (PMID 30319638, 2018). "Blocking HMGB1 release and activity reduces tumor incidence, invasion, and metastasis." (PMID 29899164, 2018). "ICD promotes the release of damage-associated molecular patterns (DAMPs), involving surface exposure of calreticulin, ATP secretion, and passive release of high-mobility group box 1 (HMGB1), raising the possibility that, as signals of danger, DAMPs facilitate anti-tumor immunity." (PMID 30282948, 2018). "The expression of HMGB1 has been investigated in several tumor models." (PMID 29472602, 2018). "Furthermore, higher HMGB1 expression in tumor tissue correlated with poor overall survival and higher HMGB1 concentration was detected in serum of patients who accepted radiotherapy." (PMID 29844348, 2018). "Furthermore, there was a significant relationship between the expression levels of HMGB1 protein and mRNA in the tumor and healthy tissues of HNSCC patients (P<0.001)." (PMID 30245980, 2018). "The HMGB1 is a cytokine and a growth factor, which can be released from tumor cell upon necrosis." (PMID 30245980, 2018). "It has been reported that NPS treatment of non-viral-transformed tumor cells results in the release of the three classical danger-associated molecular pattern molecules: calreticulin, ATP, and HMGB1, all associated with programmed cell death." (PMID 29324830, 2018). "Taken together, the results suggested that HMGB1 plays an important role in tumor progression and may be useful in the prognoses of NSCLC patients." (PMID 29850505, 2018). "Here, we reveal a new mechanism by which high mobility group box 1 (HMGB1) released by dying cells during radiotherapy or chemotherapy could stimulate living tumor cell proliferationInhibition or genetic ablation of HMGB1 suppressed tumor cell proliferation." (PMID 29844348, 2018). "Patient-matched tumor tissue showed a similar HMGB1 expression level to that of the PDX model." (PMID 30123419, 2018). "Higher expression of HMGB1 in tumor tissue predicted poor overall survival." (PMID 29844348, 2018). "We identified tumor-derived HMGB1 as a potential protein responsible for Treg phenotype induction." (PMID 30643519, 2018). "Moreover, HMGB1 derived from tumor-derived exosomes was particularly potent for inducing TIM-1+Breg cell expansion, which promoted HCC progression by impairing the function of CD8+ effector T cells." (PMID 30526680, 2018).
tumor (continued). "Studying HMGB1 complexes in the context of OV therapy could unveil new ways of promoting inflammation and immunity within the tumor microenvironment." (PMID 29543735, 2018). "Serum HMGB1 can be used as a marker to evaluate tumor stage and predict HCC prognosis in patients." (PMID 29651425, 2018). "In the present study, we provided evidence that HMGB1 released from irradiated tumor cells could stimulate the proliferation of living cells." (PMID 29844348, 2018). "miR-325 functions as a tumor suppressor by targeting HMGB1 and might serve as a potential prognostic marker for HCC." (PMID 29651425, 2018). "A recent study showed that different redox states of HMGB1 distinctly regulate tumor angiogenesis." (PMID 29636841, 2018). "In addition to its nuclear role, HMGB1 acts as an extracellular signal molecule during inflammation, cell differentiation, cell migration, and tumor metastasis." (PMID 30245980, 2018). "Most tumor cells exhibit cytoplasmic localization of HMGB1 and increased HMGB1 expression." (PMID 29636841, 2018). "In addition, HMGB1 can lead to chronic inflammation in the microscopic environment of the tumor, as well as tumor cell survival, growth, and metastasis." (PMID 30245980, 2018). "Importantly, autophagosomes can serve as vehicles to transfer a broad spectrum of contents, including tumor antigens and DAMPs (HSPs, HMGB1, S100 proteins, DNA and RNA) to different types of target cells." (PMID 30563569, 2018). "Various types of tumor-derived cell lines release HMGB1 in different conditions, such as glucose deprivation, leading to increased proliferation, migration and invasion of stromal cells involved in all stages of tumor progression through TLR4 activation." (PMID 29472602, 2018). "Additionally, HMGB1 regulates cell proliferation, cell differentiation, and tumor metastasis via various signaling pathways in HCC." (PMID 29651425, 2018). "HMGB1 is shown to be generated in a vesicle form in monocytes and tumor cells." (PMID 30292233, 2018). "Tumor irradiation led to HMGB1 releasing as well, in accordance with our finding in in vitro tumor cells, indicating that our theory (HMGB1-mediated tumor repopulation) might also be true in clinic." (PMID 29844348, 2018). "Therefore, the redox protein HMGB1 plays an important role in tumor progression by regulating immune response, angiogenesis, and the fate of cancer cells in response to anticancer therapy." (PMID 29636841, 2018). "HMGB1 expression in the tumor tissues of the cohort correlated with clinicopathological features." (PMID 29850505, 2018). "HMGB1 is highly expressed in most tumor types, including cervical cancer and breast cancer." (PMID 30279967, 2018). "Tumor cells can release HMGB1 into the local microenvironment, where HMGB1 binds with high affinity to several receptors, such as toll like receptor-2 (TLR-2), TLR-4, TLR-9 and advanced glycation end products (RAGE), which can lead to tumor cell survival, expansion and metastasis." (PMID 30526680, 2018). "Furthermore, HMGB1 released from tumor cells can increase the pro-tumoral activities of macrophages via a RAGE-dependent mechanism." (PMID 30586442, 2018). "Moreover, TLR4 signaling triggered by HMGB1 is able to stimulate an inflammatory response leading to tumor development in a skin model of tumorigenesis." (PMID 29472602, 2018). "More importantly, the study indicated that HMGB1 could mediate tumor immune escape by improving MDSC proliferation, which provided a novel theoretical basis for antitumor therapy using HMGB1 as the target." (PMID 28968989, 2017). "Maybe just like NLRP3, we speculate that NLRP1 becomes activated in tumor microenvironment by inflammatory factor, endogenous ATP, cell damage, HMGB1, or potassium efflux." (PMID 29214170, 2017). "Additionally, using xenograft mouse models, we confirmed that HMGB1 overexpression increased tumour EMT." (PMID 28727734, 2017).
tumor (continued). "The ligand HMGB-1 may inhibit antitumor immunity through interactions with Tim-3 on tumor-infiltrating dendritic cells." (PMID 29179486, 2017). "It was because the tumor cells and activated immune cells, such as macrophages, dendritic cells, and NK cells, could actively secrete HMGB1." (PMID 28968989, 2017). "Disruption of the HMGB1-RAGE autocrine loop of activation may reasonably explain the anti-tumor activity that we observed in MM using both in vitro and in vivo models." (PMID 28186988, 2017). "Ad5/3-D24-GM-CSF induces the release of HMGB1 as well as ATP in virus-infected tumor cells." (PMID 28698504, 2017). "Although much attention has been paid on the redox statuses of HMGB1, especially its effect on tumor cell autophagy and apoptosis, it is still unknown about how signaling pathways are regulated by different redox forms of HMGB1." (PMID 28969092, 2017). "Loss of HMGB1 leads to a defect in TLR9 signaling pathway and decreases tumor cell proliferation, whereas addition of HMGB1 leads to the activation of TLR9 signaling pathway and promotes tumor cell proliferation." (PMID 28969092, 2017). "In addition, some preclinical studies have demonstrated that inhibition of HMGB1 release by EP significantly increased the tumor cell sensitivity to other anticancer agents, and also protected against chemotherapy-induced cytotoxicity." (PMID 28186988, 2017). "More recently, it was found that HMGB1 could promote tumour‐infiltrating T cells to produce lymphotoxin α1β2, leading to the recruitment of CD11b + F4/80 + macrophages into the tumour." (PMID 28039939, 2017). "In addition, HMGB1 expression was closely correlated to tumor grade and T stage (p = 0.006 and p = 0.015, respectively) but not to age, gender, tumor size and number." (PMID 29069735, 2017). "sRAGE could act as a decoy to prevent RAGE signalling and has been used successfully in blocking HMGB1‐RAGE signalling pathway in animal tumour models." (PMID 28039939, 2017). "HMGB1 is a versatile protein in tumour biology and cancer therapy." (PMID 29246127, 2017). "The inhibition of RAGE‐HMGB1 by antisense S‐oligo deoxynucleotide or the 150‐183 peptide of HMGB1 (RAGE‐binding motif) could suppress tumour cell growth, migration and invasion." (PMID 28039939, 2017). "Moreover, we found that HMGB1's receptor, RAGE, is unregulated in MM tumor cells, and most MM cells actively secrete high amounts of HMGB1 into the extracellular milieu and become “addicted” to it as they require HMGB1 for growth and survival." (PMID 28186988, 2017). "As part of the bystander response of immune cells, this HMGB1 induced expression of cytokines may lead to prompting further immune action such as CD8+ T-cell or NK cell mediated killing of irradiated tumor tissue." (PMID 28638385, 2017). "The pro-lymphatic role of TLR4 is consistent with previous reports of LPS- and HMGB1-induced inflammatory lymphangiogenesis, paclitaxel-induced tumor lymphangiogenesis, and decreased ability of TLR4-deficient mice to form lymphatic vessels compared with wild-type." (PMID 28598999, 2017). "As opposed to cells undergoing a “silent” type of death like apoptosis, cells undergoing immunogenic cell death alarm the immune system by increasing surface expression of calreticulin and producing ATP and HMGB1, which trigger immune activation and initiate anti-tumor immunity." (PMID 28536346, 2017). "Interestingly, HMGB1 has also been observed to improve tumor neovascularization by attracting endothelial progenitor cells (EPCs) and mesoangioblasts." (PMID 28969092, 2017). "Zitvogel proved that dead tumor cells could release HMGB1, thus activating tumor-specific T cell immunity, and inducing antitumor effect via toll-like receptor 4 stimulating dendritic cells." (PMID 28968989, 2017).
tumor (continued). "Studies have shown that the number of tumor-infiltrating T cells was positive correlated with secretion of HMGB1 by cancer cells, specialists speculated that the underlying mechanism may be related to activation of TLR4 by HMGB1 in tumor microenvironment." (PMID 29029545, 2017). "In this study, we transfected miR-200c mimic or inhibitor into A549 cells to identify whether it can inhibit HMGB1 expression and exert anti-tumour effects." (PMID 28727734, 2017). "Importantly, we showed that extracellular HMGB1 and ATP, two critical components of the immunogenic cell death pathway, were significantly increased in the blood A antigen-expressing tumor cells." (PMID 28122343, 2017). "Based on the results indicating EP targeting HMGB1 in vitro, we evaluated whether EP may decrease HMGB1 and MM tumor growth in vivo." (PMID 28186988, 2017). "Sorafenib had a better tumour inhibition effect in the HMGB1 knockdown group in vivo." (PMID 29246127, 2017). "Interestingly, the previously reported tumor angiogenesis gene HMGB1 displays parallel actions to BRD7 knockdown as it induces the expression of different pro-angiogenic cytokines, including IL8, CXCL1 and CXCL6." (PMID 28951988, 2017). "It has been confirmed that MDSC participates in tumor immune tolerance, and the downregulation of HMGB1 in bone marrow cells in vitro could significantly inhibit the differentiation of MDSCs." (PMID 28968989, 2017). "This immunogenic cell death is characterized by the early cell surface exposure of chaperon proteins CRT, HSPs and the late cell apoptosis marker high mobility group box 1 (HMGB1), which affect dendritic cell (DC) maturation and the uptake and presentation of tumor antigens by DCs." (PMID 28282460, 2017). "In the present study, HMGB1Ab was used to down-regulate HMGB1 secretion in the tumor-bearing mice." (PMID 28968989, 2017). "HMGB1 is passively released from tumor cells after infection." (PMID 28698504, 2017). "HMGB1 expressing tumours resulted in a poor overall survival outcome." (PMID 29254158, 2017). "However, notably, despite the similar volume, immunoblotting and immunohistology staining indicated lower levels of HMGB1 and vascularization in tumor tissue, suggesting a regulation of a tumor niche." (PMID 28415753, 2017). "Moreover, we demonstrated that targeting HMGB1 inhibited MM cell growth and motility in vitro, reduced tumor growth in vivo, and prolonged survival of MM-bearing mice." (PMID 28186988, 2017). "Meanwhile, HMGB1 is significantly highly expressed in tumor tissue." (PMID 28968989, 2017). "This is important, since autophagy, although dispensable for chemotherapy-induced cell death, is required for its immunogenicity, as it enhances the release of specific DAMPs (including ATP, HMGB1, uric acid), allowing cancer cells to attract DCs and T lymphocytes into the tumor bed." (PMID 28435516, 2017). "This evidence strongly indicates that intracellular HMGB1 is a tumor suppressor of PDAC." (PMID 28374746, 2017). "HMGB1 expression can regulate the mitochondrial bioenergetics of cancer cells by enhancing complex I activity, ATP production and subsequent proliferation and migration of tumour cells." (PMID 29254158, 2017). "Additionally, it has been proposed that HMGB1 present at the cell surface promotes cell migration and tumor metastasis." (PMID 28969092, 2017). "HMGB1 which is actively released from immune cells differs from that passively released from dying tumor cells in regard of its oxidation status: the passively released HMGB1 is fully oxidized, while the actively released form has several accessible free thiol groups on its surface." (PMID 27457217, 2016). "In this context we have recently described a new mechanism by which HMGB1 could strongly influence the presence and the efficacy of NK cells at the tumor site." (PMID 27294158, 2016).